RN7SL481P (RNA, 7SL, cytoplasmic 481, pseudogene)
Gene: Miscellaneous RNA gene on chromosome 7 (143,298,516 to 143,298,814, forward strand). Ensembl gene ENSG00000240322.
Homologues: Orthologues: chimpanzee Metazoa_SRP (99% identical), macaque Metazoa_SRP (93% identical), rabbit Metazoa_SRP (67% identical). Paralogues in human: RN7SL1 (84% identical), RN7SL2 (83% identical), RN7SL3 (83% identical), RN7SL664P (82% identical), RN7SL743P (82% identical), RN7SL381P (81% identical), RN7SL45P (80% identical), RN7SL567P (80% identical), RN7SL709P (80% identical), RN7SL88P (80% identical), RN7SL431P (80% identical), RN7SL498P (80% identical), and 701 more.